IGKV1D-16 (immunoglobulin kappa variable 1D-16)
Description:
V region of the variable domain of immunoglobulin light chains that participates in the antigen recognition. Immunoglobulins, also known as antibodies, are membrane-bound or secreted glycoproteins produced by B lymphocytes. In the recognition phase of humoral immunity, the membrane-bound immunoglobulins serve as receptors which, upon binding of a specific antigen, trigger the clonal expansion and differentiation of B lymphocytes into immunoglobulins-secreting plasma cells. Secreted immunoglobulins mediate the effector phase of humoral immunity, which results in the elimination of bound antigens. The antigen binding site is formed by the variable domain of one heavy chain, together with that of its associated light chain. Thus, each immunoglobulin has two antigen binding sites with remarkable affinity for a particular antigen. The variable domains are assembled by a process called V-(D)-J rearrangement and can then be subjected to somatic hypermutations which, after exposure to antigen and selection, allow affinity maturation for a particular antigen.
Synonyms: IGKV1D16; L15; L15a
Tractability: Antibody: UniProt places it where antibodies can reach, with medium confidence; UniProt predicts a signal peptide or a membrane-spanning region; its Gene Ontology location is reachable by antibodies, with medium confidence.
Gene: Immunoglobulin variable (V) gene on chromosome 2 (90,100,236 to 90,100,738, forward strand). Ensembl gene ENSG00000241244.
Subcellular location: Secreted; Cell membrane
Pathways (Reactome):
Immune System: Antigen activates B Cell Receptor (BCR) leading to generation of second messengers; CD22 mediated BCR regulation; Classical antibody-mediated complement activation; FCERI mediated Ca+2 mobilization; FCERI mediated MAPK activation; FCERI mediated NF-kB activation; FCGR activation; Fc epsilon receptor (FCERI) signaling; Immunoregulatory interactions between a Lymphoid and a non-Lymphoid cell; Initial triggering of complement; Regulation of Complement cascade; Regulation of actin dynamics for phagocytic cup formation; Role of LAT2/NTAL/LAB on calcium mobilization; Role of phospholipids in phagocytosis
Disease: FCGR3A-mediated IL10 synthesis; FCGR3A-mediated phagocytosis; Potential therapeutics for SARS
Hemostasis: Cell surface interactions at the vascular wall
Vesicle-mediated transport: Scavenging of heme from plasma
Gene Ontology:
Molecular function: antigen binding
Biological process: immune response
Cellular component: extracellular region; immunoglobulin complex; plasma membrane
Homologues: Orthologues: mouse Igkv15-103 (77% identical). Paralogues in human: IGKV1-16 (96% identical), IGKV1-12 (93% identical), IGKV1D-12 (92% identical), IGKV1-17 (91% identical), IGKV1-9 (91% identical), IGKV1D-13 (91% identical), IGKV1-39 (90% identical), IGKV1D-39 (90% identical), IGKV1-5 (89% identical), IGKV1-27 (88% identical), IGKV1-6 (88% identical), IGKV1D-17 (87% identical), and 81 more.